NOX4 (NADPH oxidase 4)
Diseases named in the same sentence as NOX4 in open-access papers (continued):
Sharing a sentence is not in itself a finding about the gene and the disease.
heart failure (continued). "Importantly, they found that the full-length NOX4 isoform was significantly upregulated in ischemic cardiomyopathy, suggesting that NOX4 contributes to ROS production in the context of heart failure." (PMID 41009041, 2025). "Therefore, Nox4 plays a key role in Tanshinone IIA’s suppression of heart failure and myocardial fibrosis." (PMID 41011209, 2025). "Collectively, these findings highlight the need for more mechanistic studies to determine whether NOX4 is a driver of cardiac pathology or a marker of an adaptive response to stress in human heart failure." (PMID 41009041, 2025). "Notably, NADPH oxidase 4 (NOX4) has been identified to be present in mitochondria mainly and serves as a principal driver of oxidative stress in heart failure." (PMID 40564057, 2025). "Increased glycolysis is not sufficient to compensate for inadequate energy metabolism in heart failure, whereas NOX4 may improve metabolic remodeling in pathological states to improve heart function." (PMID 39867658, 2024). "Nox4 protein abundance is increased in the diaphragm of patients with heart failure." (PMID 36436728, 2023). "NOX are a key source of oxidative stress in human arteries, the NOX4-dependent effects that induced vascular dysfunction may mirror the role of this homolog in heart failure." (PMID 37980402, 2023). "Under pathological conditions such as heart failure and cardiac pressure overload, NOX4 in the mitochondria of cardiomyocytes is upregulated, reactive oxygen species increase, mitochondrial proteins are oxidized, and electrons caused by mitochondrial dysfunction." (PMID 35399278, 2022). "Moreover, high-level expression of NOX4 was shown to play essential roles in hypoxia and heart failure." (PMID 35372367, 2022). "After knocking down TLR4, autophagy and ferroptosis could be alleviated through the TLR4 and NADPH oxidase 4 (NOX4) pathway, which provides a potential treatment strategy for heart failure." (PMID 34262953, 2021). "Moreover, inhibition of endogenous expression of TLR4 and NADPH oxidase 4 that were upregulated in rat cardiac tissue after heart failure, showed heart failure relief by suppressing ferroptosis in cardiac cells." (PMID 34312370, 2021). "Nox2 and Nox4 have been identified as the main isoforms in cardiomyocytes in heart failure." (PMID 32707934, 2020). "In addition, NOX4 has been described both as detrimental and protective in mouse models of heart failure." (PMID 29204124, 2017). "Nox4-mediated ROS generation was a key signaling pathway involved in cell apoptosis which is responsible for a significant amount of the cardiomyocyte death that contributes to the development and progression of heart failure." (PMID 28230797, 2017). "Nox4 upregulation influences increases in mitochondrial oxidative stress directly and the consequent mitochondrial dysfunction and cell death during pressure overload–induced heart failure." (PMID 24887083, 2014). "Nox4 is induced in experimental models of heart failure and in humans." (PMID 23125837, 2012). "Finally, we discuss the validation of NOX4 as a potential therapeutic target for indications including stroke, heart failure, and fibrosis." (PMID 22648375, 2012). "It is likely that Nox4 expression is influenced by a multitude of factors including the severity of the lesion, the location of the blood vessel and individual factors such as other concurrent diseases such as inflammation and heart failure." (PMID 23125837, 2012). "Since expression of Nox4 is upregulated by cardiac stress, including pressure overload, heart failure and aging, upregulation of Nox4 may allow it to be a significant source of mitochondrial oxidative stress under stress conditions." (PMID 21212466, 2010).
heart failure (continued). "Nox4, localized primarily within the mitochondria, seems to be mainly responsible for increased ROS generation; however, diaphragms from patients with heart failure have shown Nox2 expression and p47phox phosphorylation highly associated with elevated protein oxidation." (PMID 32707934, 2020). "The full length NOX4 is significantly upregulated due to heart failure that might contribute to ROS production in the failing hearts, while a smaller 28-kDa isoform shows downregulation in ischemic failing hearts possibly having important roles in redox signaling of subcellular compartments." (PMID 29204124, 2017). "Interestingly, the increased expression of NOX4 in heart failure may be a compensatory effect." (PMID 39867658, 2024). "Based on bioinformatics analysis, TLR4 is a molecule upstream of NOX4, confirming that the TLR4-NOX4 pathway plays an important role in the pathogenesis of heart failure." (PMID 37600367, 2023). "NOX4 is upregulated in cardiac fibroblasts in response to TGF-β and in heart failure and is required for TGF-β-induced superoxide production, Smad2/3 phosphorylation, myofibroblast transformation, and collagen production." (PMID 36139898, 2022). "Increased oxidative stress is a major contributor to the development and progression of heart failure, however, our knowledge on the role of the distinct NADPH oxidase (NOX) isoenzymes, especially on NOX4 is controversial." (PMID 29204124, 2017). "While NOX4 inhibitors have not yet been tested clinically specifically for cardiac disease, preclinical studies suggest benefit in myocardial infarction, heart failure, and ischemia–reperfusion injury." (PMID 41009041, 2025). "Bioinformatic analysis of the transcriptional profiles of human failing hearts, obtained from patients with end stage DCM who underwent transplantation, identified NOX4 as one of six co-regulated genes (with POSTN, CTGF, FN1, LOX and TGFB2) with established link to heart failure development." (PMID 41009041, 2025). "Research on heart failure and PLB mainly focuses on the inhibitory effect of PLB on nox-4 activity." (PMID 40020101, 2025). "Accordingly, NOX4 expression was 3-fold increased in the LV from advanced heart failure patients compared to non-failing controls." (PMID 41009041, 2025). "In particular, aortic banding increased cardiac NOX4 expression and reduced cardiac GPX4 activity in animal models indicating that ROS and ferroptosis are likely involved in the process proceeding from hypertrophic cardiomyopathy to heart failure." (PMID 36980208, 2023). "Similarly, puerarin, a phytoestrogen with antioxidant properties was shown to reduce NOX4 expression and to increase GPX4 expression in the heart failure rat model." (PMID 36980208, 2023). "To determine whether heart failure and aerobic exercise had any influence at the transcriptional level, we evaluated the gene expression of two NADPH oxidase homologs (Nox2 and Nox4) and their regulatory subunits p22phox and p47phox." (PMID 37362442, 2023). "However, recent studies demonstrate that in heart failure rats, TLR4 and NOX4 expression is significantly increased, autophagy and ferroptosis are enhanced, as well as the heart function is abnormal." (PMID 34513812, 2021). "NOX4, as the most widely distributed isoform of the catalytic NADPH oxidase subunits (NOX), has been demonstrated to be a promising therapeutic target for diseases including stroke, fibrosis, and heart failure." (PMID 27276705, 2016). "While NOX4 inhibitors have not yet been tested in clinical trials specifically for cardiac diseases, preclinical data support their potential therapeutic benefits in conditions such as myocardial infarction, heart failure, and ischemia–reperfusion injury." (PMID 41009041, 2025). "The NOX4-dependent effects that induced vascular dysfunction may not mirror the role of this homolog in heart failure." (PMID 37980402, 2023).
heart failure (continued). "However, while EPO treatment increased expression of these heart failure-associated genes in WT mice, EPO treatment did not change expression of heart failure-associated genes Cdk8, TGFβ2, and NOX4 and hypertrophic cardiomyopathy-related genes Nppa in nNOS−/− mice." (PMID 38628440, 2024). "Therefore, upregulation of NOX4, but not NOX2, increases mitochondrial dysfunction, leading to apoptosis of cardiac myocytes and heart failure in response to pressure overload and chronic catecholamine stimulation." (PMID 35148678, 2022).
breast carcinoma (50 papers, 2010 to 2025). "The diagnostic potential of NOX4 is rooted in its abnormal expression in cancer tissues, including but not limited to breast cancer, lung cancer, colorectal cancer, and pancreatic cancer." (PMID 38663913, 2024). "Gain and loss-of-functional studies showed that NOX4 accelerated sphere growth, produced more stem factors, and helped maintain the features of breast cancer CSCs, indicating that NOX4 was involved in malignant cell differentiation." (PMID 38012557, 2023). "The biological roles of NOX4 in breast cancer development and the underlying biochemical mechanisms remain a mystery." (PMID 38012557, 2023). "In breast carcinoma cells, it was discovered that NOX4 was overexpressed, and this increase was linked to a poor prognosis." (PMID 38012557, 2023). "Studies have reported that NOX4 is located in mitochondria and is associated with the generation of mtROS in both breast cancer cells and renal cells." (PMID 36964576, 2023). "The gain and loss-of-function assays showed enhanced NOX4 breast carcinoma cell proliferation, sphere-forming capacity, and tumor development." (PMID 38012557, 2023). "Of note, NOX4 upregulation associated with an ROS increase has also been described by other authors in human breast cancer lines." (PMID 35163066, 2022). "The anti-cancer activity of coumarin in breast cancer has been linked to protective autophagy through NOX4-dependent ROS production." (PMID 33567693, 2021). "We have previously shown that TGFβ released from the bone matrix during osteolysis due to breast cancer bone metastases causes oxidative stress and skeletal muscle Ca2+ leak and weakness via the TGFβ-Nox4-RyR1 axis." (PMID 29312148, 2017). "The findings of this study showed that breast carcinoma cell lines produced more NOX4, which may be associated with a poorer prognosis." (PMID 38012557, 2023). "As Nox4 mRNA levels are also elevated in nonprostate tumors, findings herein are also expected to be relevant to other tumor types with a prominent stromal component (e.g., pancreatic ductal carcinoma and cancer of the breast, lung and liver) where a role of Nox4 has been implicated." (PMID 29441570, 2018). "TGFβ released from bone metastases induced the overexpression of the NADPH oxidase 4 (Nox4), leading to oxidative stress and ryanodine receptor (RyR1) oxidation, ultimately causing calcium leaking and skeletal muscle weakness in mice bearing osteolytic breast cancer cell line 4T1." (PMID 33202621, 2020). "Continuous overexpression of NOX4 has been observed in breast cancer, colorectal cancer, clear cell renal cell carcinoma, and lung cancer compared to normal tissues, suggesting its potential as a universal cancer biomarker." (PMID 38663913, 2024). "In this study, we investigated KA’s role in regulating PPARγ activity and its anti-inflammatory and anticancer effects mediated by NOX4-induced ER stress signaling pathways and apoptosis in breast cancer." (PMID 39770941, 2024). "FAD-mediated NOX4 activity and NOX4 expression induced ROS and intracellular Ca2+ production, apoptosis, and the ER stress response in breast cancer cell lines." (PMID 39765861, 2024). "FAD mediates PPARγ activity and induces apoptotic cell death through the PERK -eIF2α-ATF4-CHOP axis, the upregulation in Nox4 expression, and the production of cytosolic Ca2+ and ROS in breast cancer cells." (PMID 39765861, 2024). "The aim of this study was to investigate the role and mechanism of NOX4 in glycolysis in breast cancer." (PMID 37670970, 2023). "Three different CRISPR-mediated KO methods, including “CRISPR excision,“ “CRISPR HDR,“ and “CRISPR du-HITI,“ were used to change the position of NOX4 in several breast cancer cell lines." (PMID 38012557, 2023). "In the current investigation, NOX4 was discovered to be a carcinogenic agent in the growth of breast cancer tumors." (PMID 38012557, 2023). "Researchers conducted experiments to learn more about how NOX4 regulated the aetiology of breast cancer." (PMID 38012557, 2023).
breast carcinoma (continued). "The results showed that the expression of NOX4 in two breast cancer cell lines MDA-MB-231 and MDA-MB-453 was significantly higher than in normal epithelial cells MCF10A." (PMID 37670970, 2023). "Utilizing RT-qPCR, MTT, and a colony formation assay, the functional effects of NOX4 genetic mutation in CRISPR-excision, CRISPR-HDR, and CRISPR du-HITI knockdown cell lines of breast cancer were verified." (PMID 38012557, 2023). "In summary, NOX4 affects glycolysis and proliferation and migration of breast cancer cells through the ROS/YAP pathway." (PMID 37670970, 2023). "At the same time, the 18F-FDG imaging was used for PET scanning to evaluate the effect of the NOX4 inhibitor on aerobic glycolysis in breast cancer." (PMID 37670970, 2023). "Nodakenin induced apoptosis and upregulated ER stress-related proteins (the phosphorylation of PERK and eIF2α and the expression of GRP78, CHOP, and ATF4) via the upregulation of Nox4 and ROS and Ca2+ release in breast cancer cells." (PMID 36830050, 2023). "To investigate the expression of NOX4 in breast cancer, we detected NOX4 expression in MDA-MB-231, MDA-MB-453, and MCF-10A cells by western blotting and qRT-PCR." (PMID 37670970, 2023). "Subsequently, we used siRNA to silence NOX4 expression in breast cancer cell lines, while the NOX4-OE vector was used to over-expression NOX4 levels in breast cancer cell lines for subsequent experiments." (PMID 37670970, 2023). "To further verify the effects of NOX4 on glycolysis and metastasis of breast cancer cells, we conducted in vivo experiments." (PMID 37670970, 2023). "Based on the analysis of the experimental results above combined with the auxiliary verification MicroPET imaging findings in animal experiments, this study demonstrates that NOX4 affects the aerobic glycolysis of breast cancer." (PMID 37670970, 2023). "We then performed a microarray database analysis to query the expression levels of Nox4 in breast carcinomas and their stroma vs. normal stromal breast tissues." (PMID 35836253, 2022). "Our findings were based on an analysis of human arteries, and we gained additional mechanistic insight from studies of WT and Nox4–/– mice, providing possible mechanisms of long-term vascular disease in breast cancer survivors." (PMID 35617030, 2022). "Together these studies indicate a role of redox signaling via the Nox4-Nrf2 pathway in tumorigenesis and metastasis of breast cancer cells by promoting autophagy and survival of CAFs." (PMID 35836253, 2022). "Our in situ RNA hybridization analysis for Nox4 transcription on a human breast tumor microarray further support a role of this pro-oxidant in the stroma of breast carcinomas." (PMID 35836253, 2022). "It has been indicated that NOX4 promotes cells migration in CC, breast cancer as well as pancreatic cancer." (PMID 36249057, 2022). "Although NOX4 is not differentially expressed in different stages of breast carcinoma, our previous breast cancer models showed a strong NOX4 influence on cell invasiveness." (PMID 33557266, 2021). "For example, tumor metastasis is reduced in a mouse breast cancer xenograft model in which Nox4 expression was silenced in 4T1 cells, and angiogenesis was reduced in carcinogen-induced fibrosarcomas in Nox4 knockout mice." (PMID 33557266, 2021). "The ROS inhibitors diphenyleneiodonium and N-acetyl cysteine suppressed apoptosis and excessive ER stress by inhibiting Nox4 in JI017-treated breast cancer cells." (PMID 34942984, 2021). "In breast cancers, Smad3 controls Nox4, and in pancreatic cancers, Nox4 delivers ROS for the EMT phenotype switch." (PMID 34947978, 2021). "Meanwhile, overexpression of HSPA2 was related to tumor angiogenesis and poor prognosis of pancreatic cancer, while the survival prognosis of breast cancer patients with high expression of NOX4 was poor, too." (PMID 33240321, 2020).